CCR2 (C-C motif chemokine receptor 2)
Diseases named in the same sentence as CCR2 in open-access papers (continued):
Sharing a sentence is not in itself a finding about the gene and the disease.
tumor (continued). "Given our data on how CCR2 gene deletion reduced MDSC and Treg infiltration and increased intratumoral accumulation of activated CD8+ T cells, we undertook a corresponding analysis of cells present within the tumor microenvironment of WT mice receiving vehicle or CCR2 antagonist therapy." (PMID 33322474, 2020). "We found the CCR2 antagonist markedly impaired tumor growth." (PMID 33322474, 2020). "How could these observations take place with the predominate role of the CCR5-axis for directing PMN-MDSC recruitment and the CCR2-axis for M-MDSC selective recruitment at tumor sites?" (PMID 33193327, 2020). "Thus, the relevance of CCR2 on tumor progression varies and depends on the tumor’s environmental context and location." (PMID 32668709, 2020). "Blockade of CCR2 or CCR5 has been shown to inhibit tumor progression in some animal models." (PMID 32001710, 2020). "We observed that, at 10 d.p.i., CCR2+ immune cells infiltrated the brains of tumor mice and accumulated in the VI Interestingly, a large percentage of neutrophils in the VI were CCR2+, which infiltrated throughout the VI and often formed large aggregates consisting of 20 cells or more." (PMID 32391790, 2020). "Additionally, blocking CCL2, or its receptor CCR2, reduces tumor growth and metastases, and this mechanism is currently being target in the clinic." (PMID 32528880, 2020). "However, 70% of myeloid cells infiltrate the tumor tissue independently of the CCR2/CCL2 signaling axis." (PMID 32668709, 2020). "Nonetheless, this anti-inflammatory activity of ACKR2 not always is beneficial, because this receptor may also lead to a reduced CCR2 expression by NK cells and limiting their infiltration of tumor tissue, what finally supports metastasis." (PMID 32456359, 2020). "Moreover, compared to TAMs from WT tumor-bearing mice, those from Ubr5−/− tumor-bearing mice exhibited higher levels of M1 macrophage markers (e.g., il12a, Ccr2) and lower levels of M2 markers (e.g., Cx3cr1, il10)." (PMID 33293516, 2020). "Neutralizing CCL2, or its receptor CCR2, reduces tumor growth and metastases." (PMID 32528880, 2020). "TAMs were isolated from naïve and tumor-bearing wildtype (WT) as well as Ccr2-/- (Ccr2KO) mice." (PMID 32668709, 2020). "Lastly, given the importance of CCR2+ MDSC recruitment to promoting tumor growth in our studies, we assessed whether production of MCP-1/CCL2 was host derived or tumor derived by testing syngeneic tumor growth in WT vs. MCP-1KO mice." (PMID 33322474, 2020). "The results indicated that CCR2 knockout blocks the SARI deficiency‐mediated tumorigenesis, as evidenced by representative mini‐endoscopic images, tumour multiplicity analysis, tumour area analysis and colon length analysis." (PMID 31578820, 2020). "Considering the role of FROUNT as a common regulator of chemokine receptors CCR2 and CCR5, which have been implicated in tumor progression, we hypothesized that FROUNT expression levels affect clinical outcomes." (PMID 32001710, 2020). "Furthermore, it was reported that CCL2/CCR2 axis indirectly promotes tumor progression by increasing the recruitment and suppressive activity not only TAMs, but also MDSCs, the immunosuppressive cells of myeloid origin." (PMID 32456359, 2020). "Additionally, kynurenine-activated AHR signaling was found to elevate C-C chemokine receptor type 2 (CCR2) expression, leading to monocyte recruitment and increased tumor growth in vivo." (PMID 33171762, 2020). "Taken together, ablation of CCR2-MCP1 signaling boosts anti-tumor efficacy by preventing the tumor infiltration of immunosuppressive CCR2+ M2 MDSCs and by promoting cytotoxic T cell responses, and may serve as a new therapeutic component in immuno-oncology." (PMID 33322474, 2020). "The basis for the CCR2 antagonist leading to an M1 phenotype of MDSCs present at the tumor site in our studies is currently unknown, though there are some clues from the literature." (PMID 33322474, 2020).
tumor (continued). "This indicates that the CCL2/CCR2 axis participates in the recruitment of TAMs into tumor tissues." (PMID 33224886, 2020). "Use of this CCR2 antagonist promoted anti-tumor immunity and limited tumor growth." (PMID 33322474, 2020). "Blocking CXCR2 on MDSCs has shown to increase the efficacy of tumor regression in CCR2 KO mice." (PMID 33374595, 2020). "Again, we observed similar tumor growth in Ccr2–/– and Ccr2+/+ mice." (PMID 32780724, 2020). "In a mouse liver cancer model, fibroblast activation protein (FAP)–STAT3–CCL2 signaling in cancer-associated fibroblasts (CAFs) promoted tumor growth by enhancing MDSC mobilization and FAP-mediated tumor promotion, and MDSC mobilization in CAF was abolished in CCR2-deficient mice." (PMID 33297571, 2020). "Then Ly6C+CCR2+ monocytes are engaged into tumor tissue and differentiated into TAMs." (PMID 33224886, 2020). "We looked to test the efficacy of targeting CCR2 in combination with PD-1 in multiple tumor models." (PMID 33247183, 2020). "According to the elevated expression of chemokine CCL2 in cancer cells and tumor tissues, we speculate CCR2 may correlate with tumor tropism of EVs as their donor cells." (PMID 32550891, 2020). "Use of CCR2-knockout (CCR2-KO) mice showed dependence of tumor growth on CCR2 signaling." (PMID 33322474, 2020). "In summary, the cooperation between tumor-derived chemokines and host/adipose tissue-derived chemokines, particularly CCL2, through CCR2 signaling considerably contributes to tumor cell survival, proliferation, and metastasis, which makes CCR2 a potential therapeutic target in cancer treatment." (PMID 32471499, 2020). "In a preclinical model of HCC, blocking CCL2/CCR2 signaling with a CCR2 antagonist reduced Ly6Chi monocyte numbers in the peripheral blood and suppressed anti-inflammatory macrophage polarization in the liver, ultimately inhibiting tumor growth." (PMID 32047496, 2019). "Indeed, neutrophils can compensate for macrophages to support tumor angiogenesis in tumor-bearing CCR2-knockout mice." (PMID 31572387, 2019). "Growing preclinical studies showed that targeting TAMs by blocking the CCL2/CCR2 axis inhibited the tumor development and might be a potential therapeutic revenue for several malignancies." (PMID 31024838, 2019). "In addition, a small molecule CCR2 inhibitor (PF-04136309) was applied in a preclinical pancreatic cancer mouse model, which resulted in reduced tumor growth and fewer liver metastases by reducing the recruitment of inflammatory monocytes to the tumors." (PMID 31497026, 2019). "Accumulating evidence indicates that monocytes (primarily iMo) are essential pre-metastatic promoters being rapidly recruited from the bone marrow to the pre-metastatic niche, mainly by CCL2/CCR2 axis, where they promote tumor colonization by secreting angiogenic factors, like VEGFA." (PMID 31447834, 2019). "And the expression of CCR2 was significantly associated with the clinical stage and perineural invasion (P < 0.05), whereas not with age, gender, tumor site, tumor histotype, and distant metastasis of SACC (P > 0.05)." (PMID 31024838, 2019). "We established the tumor xenograft mice model with SACC-83 cells to investigate whether blocking the CCL2/CCR2 axis by the CCR2 antagonist could inhibit the development of SACC." (PMID 31024838, 2019). "CCR2 was found in the cytoplasm of tumor cells and stromal cells in SACC tissues." (PMID 31024838, 2019). "The fibrous stroma can be circumvented by locoregional administration, or designing CAR T-cells to target antigens that are expressed by both the tumor and cancer-associated stroma such as Fibroblast Activation Protein, or by adding chemokine receptors such as CCR2 to enhance trafficking to tumor." (PMID 31867277, 2019). "Since CCL2 was critical for myeloid cells accumulation in residual tumor, we assessed whether targeting myeloid cells with CCR2 antagonist (CCR2a) could inhibit the growth of the residual tumor." (PMID 31780645, 2019).
tumor (continued). "Moreover, a previous study has found that targeting CCL2/CCR2 signaling with a CCR2 antagonist significantly reduces the recruitment and polarization of TAMs and thus enhances tumor immunotherapeutic effect." (PMID 30894684, 2019). "Further Targeting C-C motif chemokine receptor 2 (CCR2) or colony stimulating factor 1 receptor (CSF1R) rallies chemotherapeutic efficacy inhibits metastasis and increases anti-tumor T-cell responses by causing a reduction in the number of tumor-initiating cells (TICs) in PDAC." (PMID 30925924, 2019). "In addition, trapping of tumor cells in small capillaries can initiate tumor cell extravasation, which is related to CCR2+ myeloid cells and the CCR2+ endothelium." (PMID 30871117, 2019). "For example, we reported recently that the ARB losartan exerts potent antitumor activity by blocking signaling via the CCR2 chemokine receptor, thereby inhibiting the recruitment of inflammatory monocytes into tumor tissues, leading to overall tumor macrophage depletion." (PMID 32010120, 2019). "Inflammatory CC (CCL2, CCL3, CCL5) and CXC (CXCL1, CXCL2, CXCL5, CXCL6, and CXCL8) chemokines recruit at the tumor site CCR2+ monocytes and CXCR2+ neutrophils that differentiate into tumor associated macrophages (TAMs) and tumor associated neutrophils (TANs), exerting pro- or anti-tumoral role." (PMID 30894861, 2019). "The group that received CCR2+HSCs HSCs expressed the highest amount of CD3+YFP+ cells within the tumor microenvironment where an average of 42% ± 6.84% of CD3+ cells were found to be YFP+, more than the groups that received any of the other progenitor cell populations." (PMID 30333482, 2018). "The cohort that received intratumor CCR2+HSCs had endogenous T cells isolated from tumor draining lymph nodes that mounted the capacity to recognize Ptc tumor cells, secreting IFNγ upon co-culture against Ptc tumor cell targets." (PMID 30333482, 2018). "In addition, co-transfer of CCR2+HSCs with adoptive cellular therapy leads to the persistent activation status of adoptively transferred tumor-reactive T cells." (PMID 30333482, 2018). "The role of CCL2 in the development of tumor is mediated through its receptor CCR2." (PMID 29458367, 2018). "Interestingly, work by Kang and Lu showed that ectopic expression of CCL2 in 231_LM2 cells enhanced experimental metastasis to lung via recruitment of tumour-promoting lung macrophages that display its cognate receptor CCR2." (PMID 29720474, 2018). "In PDA mouse models, CCR2 inhibition depleted inflammatory monocytes and macrophages, which resulted in enhanced chemotherapy efficacy and anti-tumor T-cell response while inhibiting tumor cell growth and metastasis." (PMID 29891787, 2018). "Similarly, genetically engineered CCR2 expression on CAR T cells directed to the tumor antigen mesothelin increased tumor cell infiltration and anti-tumor responses against large and established tumors inoculated in severe immunodeficient mice." (PMID 30420855, 2018). "We found that intravenously administered CCR2+HSCs migrate preferentially to the CNS tumor microenvironment, differentiate into CD11c+ APCs at the tumor site, and reprogram gene expression within the immunosuppressive tumor microenvironment, while targeting multiple suppressive pathways at once." (PMID 30333482, 2018). "However, it has been recently demonstrated that ACKR2 also hinders tumor infiltration of NK cells by limiting their expression of CCR2, finally supporting metastasis." (PMID 30591657, 2018). "Additionally, CCR2 knockout mice that have fewer TAMs have reduced tumor uptake of MR-targeted nanobodies, indicating that MR binding is through CCR2 derived cells, including macrophages." (PMID 29670528, 2018). "Thus, tumor-resident MSCs drive tumorigenesis via the chemokine-CCR2-positive monocyte/macrophage axis." (PMID 29915688, 2018).
tumor (continued). "Additionally, utilization of CCR2 knockout mice showed the dependence of progression of TC1 tumor on CCR2 signaling (tumors were significantly smaller in CCR2KO mice compared to WT mice)." (PMID 30400822, 2018). "Importantly, we demonstrate that the cells derived from the transferred CCR2+HSCs actually downregulate the expression of CCR2 within the tumor." (PMID 30333482, 2018). "Interestingly, we found that tumour-resident MHCIIhi and MHCIIlow macrophages both expressed relatively low levels of CCR2 compared to their LP counterparts and, consistently, their numbers did not change in Ccr2−/− mice." (PMID 29422500, 2018). "Similarly, tumor infiltrating CCR2-positive monocytes/macrophages have a strong tumor-promoting effect." (PMID 29915688, 2018). "Treatment with a CCR2 antagonist inhibited HCC tumor growth in different murine models." (PMID 30410942, 2018). "CCL2 recruits monocytes with CCR2 from the peripheral blood to tumor site and interacts with them." (PMID 29458367, 2018). "Furthermore, and given that CCL2 expression is a common feature of tumors, our data suggest that enhancing CCR2 expression by NK cells will increase their migration into tumor sites and enhance killing of nascent metastatic deposits." (PMID 30158126, 2018). "Taken together, these data assert that the tumour microenvironment can modify the properties of MHCIIhi tissue-resident macrophages such that they also become CCR2 independent like MHCIIlow cells in the LP and hence are presumably able to maintain themselves without monocyte replenishment." (PMID 29422500, 2018). "Relative amounts of DsRed+CCR2+HSCs vs. GFP+CCR2−HSCs were measured within the tumor." (PMID 30333482, 2018). "In a lymphoma model, inhibition of CCR2 in monocytes reduced tumor size and number of TAMs." (PMID 29670528, 2018). "In line with a functional involvement of alternatively activated myeloid cells in influencing tumor burden, the infiltration of pLKO.1 versus shTRAIL-R 3LL tumors was significantly decreased by shTRAIL-R in WT, but not in CCR2-deficient, mice." (PMID 28212753, 2017). "Macrophages can be recruited to tumour sites by tumour-derived CCL2 that binds to CCR2." (PMID 28210073, 2017). "MMTV-PyMT mice with a genetic deletion of either CCL2 or CCR2 exhibited earlier onset of tumor growth and increased metastasis, though the rate of primary tumor growth was enhanced, implying an anti-tumor role for CCL2 in early stages of tumor progression and in metastasis." (PMID 28143493, 2017). "In addition, mice with a complete response to IR + anti-CCR2 treatment were resistant to tumor re-challenge, further confirming the establishment of tumor-specific adaptive memory response." (PMID 29170400, 2017). "In addition, CCR2+ M-MDSCs commonly found in various types of cancers can facilitate tumor cell extravasation and metastatic outgrowth." (PMID 29170400, 2017). "However, there was tumor relapse in some animals, presumably due to immunosuppression induced by interferon stimulation via influx of CCR2+Ly6Chi monocytic MDSC." (PMID 29170400, 2017). "We identify endogenous TRAIL-R-induced CCL2 and its activity on host-derived CCR2-expressing cells as crucial for the formation of a tumor-supportive myeloid compartment because TRAIL-R-dependent differences in tumor burden were observed in WT, but not in CCR2-deficient, mice." (PMID 28212753, 2017). "Interestingly, if the original IRISOE tumor cells CM was from hypoxic cells even further increase in CCR2 expression on the surface of THP1-macrophages was observed (lower)." (PMID 29262555, 2017). "Because TRAIL/TRAIL-R-induced CCL2 elicited its tumor-supportive effect via CCR2, we also determined whether, and if so, which, immune cell markers and cytokines were co-regulated with composite TRAIL/CCR2 expression." (PMID 28212753, 2017). "CCR2+ endothelial cells play a prominent role in tumor cell metastasis." (PMID 29170400, 2017).
tumor (continued). "Although it is unclear whether tumor cells of PDAC tissues have CCR2, presence of CCR2 was shown in preinvasive PanIN lesions of transgenic KC mice." (PMID 29379802, 2017). "Importantly, this TAM population was recruited directly from CCR2+ inflammatory monocytes that proliferated and differentiated into TAMs in the tumour microenvironment." (PMID 28210073, 2017). "Although TRAIL’s immunomodulatory effects could be attributed to a TRAIL/TRAIL-R–CCL2/CCR2 axis, it is important to note that TRAIL’s cancer secretome includes several other cytokines associated with tumor-supportive functions." (PMID 28212753, 2017). "CCR2 -/- mice had attenuated tumor growth compared to wild-type mice." (PMID 28045930, 2017). "These experiments also clarified whether the enhanced efficacy of radiation on tumor regression in CCR2−/− mice was due to a congenic intrinsic development defect in trafficking and maturation of myeloid-derived cells in the knockout mouse." (PMID 29170400, 2017). "Blockade of either CCL2 or CCR2 has shown pre-clinical anti-tumor success." (PMID 28467800, 2017). "In accord with our hypothesis, Ccr2−/− mice were protected against MPE induced by all three Kras-mutant tumour cell lines and displayed reduced CCR2 expression by pleural fluid cells and decreased accumulation of CD11b+Gr1+ cells in the pleural space." (PMID 28508873, 2017). "However, when combined with radiation, anti-CCR2 significantly enhanced the efficacy of tumor regression compared to IR alone (144 ± 71 vs. 540 ± 151 on day 43, P < 0.01: Student’s t-test)." (PMID 29170400, 2017). "CCR2 has been widely studied since its discovery of role in mediating the recruitment and migration of monocytes into the target sites along with its major ligands gradient, which was secreted by both tumor and stromal cells." (PMID 26992207, 2016). "Similarly, we identified CCL2/CCR2 axis as a tumor promoter in NPC metastasis through upregulating MMP2/9 via ERK1/2 pathways." (PMID 26701209, 2016). "Importantly, several myeloid cell chemoattractants are increased across different tumor tissues including the predominate ligand for CCR2+ IM: CCL2." (PMID 27852031, 2016). "In order to assess whether the improvement in homing is reflected in in vivo anti-tumor activity, we decided to monitor tumor growth in vivo during ACT with CCR2- or control-transduced CD8+ T cells." (PMID 27177227, 2016). "Targeting the CCL2/CCR2 axis is promising as it results in blocking mobilization of monocytes from the bone marrow to the blood, which results in preventing their recruitment to the tumor." (PMID 27191744, 2016). "A previous study showed that tumor-educated mesenchymal stromal cells recruit macrophages via CCR2." (PMID 26988913, 2016). "In summary, our study has identified and proven that infiltrated mast cells could enhance BCa metastasis via stimulating the ERβ/CCL2/CCR2/EMT/MMP9 signaling pathway in the BCa tumor microenvironment." (PMID 26556868, 2016). "CCL2 binds the cognate receptor CCR2, and together this signaling pair has been shown to have multiple pro-tumorigenic roles, from mediating tumor growth and angiogenesis to recruiting and usurping host stromal cells to support tumor progression." (PMID 26885690, 2016). "Our results raise the possibility that Ccr2 deletion may produce changes that lead to paradoxical effects on HER2/neu-driven tumor growth." (PMID 27820834, 2016). "CCL2 and CCR2 positive staining were mainly located in the cytoplasm of the tumor cells." (PMID 27409666, 2016). "We hypothesize that the efficacy of CCR2/CCR5 dual blockade is dependent on the existence of a productive initial anti-tumor T-cell response." (PMID 27852031, 2016). "Ranitidine had no impact on E0771 tumor growth in mice deficient in CCR2, where monocyte recruitment to tumors was limited." (PMID 26863636, 2016). "In addition, CCR2 expression was positively correlated with tumor size (P=0.042) and distant metastasis (P=0.028) in the validation set." (PMID 26992207, 2016).